CUX1 (cut like homeobox 1)
Diseases named in the same sentence as CUX1 in open-access papers (continued):
Sharing a sentence is not in itself a finding about the gene and the disease.
pancreatic cancer (12 papers, 2009 to 2023). "In analogy to these findings, we had previously observed that pancreatic cancer cells harboring oncogenic KRAS mutations undergo apoptotic cell death upon CUX1 knock-down." (PMID 34070180, 2021). "We could verify an important role of CUX1 as regulator of cell migration, invasion and survival, associated with high expression levels of CUX1 in several independent cohorts of pancreatic cancer tissues." (PMID 24212607, 2010). "Using two different mouse models for the prevalent CUX1 isoforms p200 and p110, we identified p110 CUX1 as the major isoform promoting pancreatic cancer formation in the context of mutant KRAS." (PMID 34070180, 2021). "In pancreatic cancer, CUX1 acts as an important mediator of tumor cell proliferation and resistance to apoptosis." (PMID 34070180, 2021). "Taken together, our data identified CUX1 as an important enhancer of KRAS-induced tumor development in pancreatic cancer, acting synergistically with oncogenic KRAS by inducing several upstream and downstream effectors such as ADAM17 and MOS." (PMID 34070180, 2021). "The Michl P group has demonstrated the overexpression of CUX1 in both tumor cells and TAMs in pancreatic cancer." (PMID 32547943, 2020). "In addition, CUX1 was enriched in tumor-associated macrophages (TAMs) and interacted with nuclear factor κB (NF-κB) p65 to attenuate the activation of NF-κB signaling, leading to a decrease in T-cell attraction and an increase in angiogenesis in pancreatic cancer." (PMID 32547943, 2020). "To further investigate the mechanistic basis of Cux1 function in mediating apoptosis repression in vertebrates, we suppressed Cux1 in Panc1 pancreatic cancer cells and determined the transcriptional response of human apoptosis genes." (PMID 22438831, 2012). "We now show that down-regulation of Cux1 in pancreatic cancer cell lines leads specifically to the transcriptional induction of the pro-apoptotic gene puma and the down-regulation of the anti-apoptotic gene Bcl-2." (PMID 22438831, 2012). "Previously, we showed that CUX1 is highly expressed in pancreatic cancer tissues." (PMID 34070180, 2021). "Based on our in vitro and in vivo data, the CUX1–EGF–MEK-ERK circuit might represent a promising target for therapeutic intervention to target KRAS-driven pancreatic cancer." (PMID 34070180, 2021). "Previously, we could show that CUX1 acts as an important mediator of tumor cell proliferation and resistance to apoptosis in pancreatic cancer cell lines." (PMID 34070180, 2021). "CUX1-induced signaling led to enhanced MEK/ERK activation, increased proliferation, accelerated PanIN formation and development of invasive pancreatic cancers." (PMID 34070180, 2021). "CUX1 can transcriptionally upregulate WNT5A and GRIA3 to reduce apoptosis and promote proliferation, migration, and invasiveness in pancreatic cancer." (PMID 32547943, 2020). "The Ripka study has demonstrated that CUX1 expression was induced by activation of Akt/protein kinase B signaling, and decreased by PI3K inhibitors in pancreatic cancer." (PMID 33344221, 2020). "Besides, CUX1 is a homeodomain transcriptional regulator known to be involved in the development and cell cycle progression, and its activity is associated with increased migration and invasiveness in numerous tumor cell lines including HCT116 or resistance to apoptosis in pancreatic cancer." (PMID 25069957, 2014). "CUX1 stabilizes Src and in turn activates its downstream signaling molecules such as RhoA, Rac1, Cdc42, and ROCK by transcriptionally upregulating C-terminal Src kinase (Csk) in pancreatic cancer." (PMID 32547943, 2020).
myeloid neoplasm (9 papers, 2014 to 2024). Proliferation of myeloid cells originating from a primitive stem cell. "Otherwise, CUX1 participates in DNA repair, and CUX1 deletion leads to abnormal DNA repair, which also seems to be one of the pathogenic mechanisms of myeloid tumors." (PMID 36408177, 2022). "Haploinsufficiency for CUX1 due to somatic mutations is associated with inferior prognosis in myeloid malignancies similar to the adverse outcome of -7/del(7q) myeloid malignancies which has been recognized for over three decades." (PMID 33931647, 2021). "Our conditional knockout mice establish that Cux1 haploinsufficiency requires cooperative mutations such as Flt3ITD to induce the spectrum of -7/del(7q) myeloid malignancies as observed in humans." (PMID 33931647, 2021). "Loss of CUX1 function in myeloid malignancies is additionally suggested to be associated with poor prognosis." (PMID 25096479, 2014). "Recent observation that CUX1 (cut-like homeobox 1, encoding a transcription factor located at chromosome 7q22), is frequently deleted in myeloid neoplasms is noteworthy." (PMID 25096479, 2014). "In myeloid neoplasms, CUX1 deletion or mutation carries a poor prognosis." (PMID 34997000, 2022). "Furthermore, since CUX1 haploinsufficiency predominates over complete CUX1 loss in myeloid malignancies, we wished to establish the relevance of findings by comparing the impact of CFLAR depletion in CUX1-haploinsufficient cells." (PMID 33931647, 2021). "Our observations of RAS pathway co-alterations (CBL and KRAS) in the EPI6 signature aligns with the documented activation of this pathway in CUX1-altered MNs, as recently demonstrated in the context of 7q alterations in myeloid neoplasms." (PMID 38890297, 2024). "Mutational profiling revealed mutations in four genes associated with myeloid malignancies, namely, EZH2, CUX1, TET2, and BCOR." (PMID 33628448, 2021). "Recently, myeloid neoplasms with germline DDX41 variants were shown to have a higher proportion of somatic CUX1 variants compared with those without a known germline background." (PMID 38203823, 2024). "In myeloid malignancies, CUX1 falls within the commonly deleted region of chromosome 7q2223." (PMID 34997000, 2022).
Obesity (9 papers, 2017 to 2024). Accumulation of substantial excess body fat. "Another study of DNA methylation in whole blood and the association with obesity observed the association between DNA methylation changes of Ddah2, Cux1, Notch4, and Dst with BMI." (PMID 35458198, 2022). "Regarding CUX1-related researches, the methylation modifications of CUX1 have been proven to be associated with complex biological processes, including amygdala and hippocampus development, chronic kidney disease and obesity." (PMID 37895221, 2023). "CUX1 and its related pathways such as the AMPK pathway could therefore be an important target of breastfeeding and might potentially play a role in modulating the risk of obesity in individuals carrying variants in the FTO gene." (PMID 34937578, 2021). "CUX1-mediated upregulation of RPGRIP1L by binding to FTO intron 1 may reduce leptin sensitivity and lipolysis, promoting the development of obesity." (PMID 39125332, 2024). "CUX1, NANOG, GATA4 and HIF1A plays a vital role in the patients with obesity." (PMID 36837510, 2023).
atherosclerosis (6 papers, 2022 to 2026). A disease characterized by the build-up of fatty material and calcium deposition in the arterial wall resulting in partial or complete occlusion of the arterial lumen. "Our recent findings showed that CUX1 is an activator of p16INK4a, regulating p16INK4a-dependent cellular senescence via its binding to an atherosclerosis-associated fSNP rs1537371 on the CDKN2A/B locus." (PMID 38944813, 2024). "CUT-like homeobox 1 (Cux1) regulates p16INK4a-dependent cellular senescence in ECs and VSMCs by binding to atherosclerosis-associated functional SNP (fSNP) rs1537371 on the CDKN2A/B gene locus." (PMID 39519014, 2024). "We demonstrate that this regulation occurs via the specific binding of CUX1 to an atherosclerosis-associated fSNP, rs1537371, on the CDKN2A/B locus." (PMID 37117763, 2022). "Our post-GWAS functional analysis revealed that cathepsin L (CTSL) is an upstream regulator of CUX1, and it induces p16INK4a-dependent and atherosclerosis-associated senescence by indirectly activating CUX1 transcription in a process that requires its proteolytic activity." (PMID 42210653, 2026). "Previously, we identified CUX1 as an activator of p16INK4a‐dependent cellular senescence in response to telomere shortening, DNA damage, and oxidative stress via its specific binding to an atherosclerosis‐associated fSNP rs1537371 on the CDKN2A/B locus." (PMID 36633253, 2023). "Remarkably, we also demonstrate that IL‐1β, a senescence‐associated secretory phenotype (SASP) gene itself and a biomarker for atherosclerosis, induces cellular senescence also by upregulating CUX1 and/or downregulating SATB2 in human ECs." (PMID 36633253, 2023). "Our findings reveal a new role of CUX1 in regulation of cellular senescence and provide new insights into how genetic variants in the CDKN2A/B locus can modulate susceptibility to atherosclerosis and other age-related complications." (PMID 37117763, 2022). "We believe that these findings reveal a mechanism implicating CUX1 as an inducer of cellular senescence and, hence, as a potential driver of age-related diseases such as atherosclerosis." (PMID 37117763, 2022). "Therefore, together, CUX1 and SATB2 fine‐tune the expression of p16INK4a via their competitive, but also coordinated binding to the atherosclerosis‐associated fSNP rs1537371, which precisely and tightly regulates cellular senescence in human ECs." (PMID 36633253, 2023). "Thus, our studies identify CUX1 as a regulator of p16INK4a-dependent endothelial senescence and a potential therapeutic target for atherosclerosis and other age-related diseases." (PMID 37117763, 2022). "Based on this association we hypothesized that, as a direct regulator of p16INK4a, CUX1 expression might be upregulated in patients with age-related diseases such as atherosclerosis." (PMID 37117763, 2022). "Recently, we demonstrated a role of CUT-like homeobox 1 (CUX1) in regulating the p16INK4a-dependent cellular senescence in human endothelial cells (ECs) and vascular smooth muscle cells (VSMCs) via its binding to an atherosclerosis-associated functional SNP (fSNP) rs1537371 on the CDKN2A/B locus." (PMID 38944813, 2024).
Intellectual disability (6 papers, 2022 to 2024). "In humans, variants in CUX1 have been associated with a wide variety of phenotypes including intellectual disability and developmental delay, delayed speech or language development, MRI abnormalities and heart defects (OMIM:618330)." (PMID 39103808, 2024). "Heterozygous, pathogenic CUX1 variants are associated with global developmental delay or intellectual disability." (PMID 37644171, 2023). "In summary, disease-causing CUX1 variants result in a non-syndromic phenotype of developmental delay and intellectual disability." (PMID 37644171, 2023). "A missense de novo variant of CUX1 was detected in a patient with epilepsy, autism, and intellectual disability." (PMID 36619507, 2022). "CUX1 mutation may lead to mild intellectual disability and has familial heritability." (PMID 37409103, 2023). "CUX1 is located downstream of HAR426, and pathogenic mutations in CUX1 are associated with ASD, intellectual disability and epilepsy." (PMID 39516464, 2024).
colorectal cancer (5 papers, 2017 to 2026). A primary or metastatic malignant neoplasm that affects the colon or rectum. "Elevated expression levels of PAX6, BCL11B, MCOLN2, CUX1 and EMX1 reported in colorectal cancer positively correlate with TRPA1 in other malignancies, with a possible implication in tumorigenesis." (PMID 39770499, 2024). "To investigate the impact of CUX1 DNA repair function on radioresistance, we established populations of DLD-1 colorectal cancer cells and retinal pigment epithelial (RPE1) cells stably expressing the CUT domains 1 and 2 protein, C1C2-NLS." (PMID 28147323, 2017).
epilepsy (5 papers, 2022 to 2024). A brain disorder characterized by episodes of abnormally increased neuronal discharge resulting in transient episodes of sensory or motor neurological dysfunction, or psychic dysfunction. "Although epilepsies observed in patients with CUX1 and CASP variants were rather heterogeneous, CASP-p.G563S and p.F623del variants appeared in mTLE and lTLE patients, respectively." (PMID 35581205, 2022). "We analyze brain CUX1 expression and susceptibility to epilepsy in Cux1+/− mice." (PMID 37644171, 2023). "Furthermore, our results with the mouse model demonstrate a reduction of Cux1/CUX1 expression in heterozygotes and support a causative link between disease-causing CUX1 variants and epilepsy." (PMID 37644171, 2023). "A recent RNAseq study of human epilepsy identified layer II–III Cux1-positive principal neurons and layer V Fexf2-positive neurons as possible drivers of excitability perturbations in the neocortex." (PMID 37887298, 2023). "No other truncation variants of the CASP-specific sequence were found in these databases, suggesting that CUX1 and especially CASP variants contribute to epilepsy." (PMID 35581205, 2022). "We performed targeted sequencing analyses of CUX1 and CASP in the 271 Japanese patients with epilepsy and identified nine nonsynonymous variants." (PMID 35581205, 2022). "For instance, the miRNA rno-let-7c-5p is dysregulated in human epilepsy and inferred mRNA targets present in multiple other resources include Cux1 (Cut like homeobox 1), Il1a (Interleukin 1 Alpha), Msn (Moesin), Nat8l (N-acetyltransferase 8 like) and Wapl (WAPL cohesin release factor)." (PMID 38961125, 2024). "In this study, we performed targeted sequencing analyses of CUX2, CUX1 and CASP on 271 Japanese patients with a variety of epilepsies, and found that CUX2 missense variants predominantly appear in TLE patients, in that eight of 68 TLE patients (12%) had CUX2 variants." (PMID 35581205, 2022). "Moreover, our mouse studies suggested that epilepsy is part of CUX1-related NDD, thus supporting the notion that missense variants in CUX1 could indeed be causative." (PMID 37644171, 2023).
glioma (5 papers, 2021 to 2023). A benign or malignant brain and spinal cord tumor that arises from glial cells (astrocytes, oligodendrocytes, ependymal cells). "CUX1 can regulate β-catenin expression and activate the Wnt/β-catenin signaling pathway in gliomas, and, when CUX1 is knocked down, the expression of β-catenin at the mRNA and protein levels is suppressed." (PMID 36833350, 2023). "Considering the main expressed CUX1 isoform in glioma is P75CUX1, our study revealed that targeting P75CUX1 was a potential effective strategy for glioma therapy." (PMID 33542188, 2021). "Both WB findings on cell lines and IHC data from glioma xenograft specimens indicated that the expression of total β-catenin was decreased when CUX1 knockdown, and nuclear accumulation of active β-catenin were also relatively lower." (PMID 33542188, 2021). "Taken together, the results indicated a highly dependent causal relationship of CUX1, β-catenin, and EMT in glioma progression." (PMID 33542188, 2021). "Collectively, CUX1 regulated the expression of total β-catenin and nuclear activity of β-catenin in glioma." (PMID 33542188, 2021). "Through gene set enrichment analysis (GSEA), we identified and predicted the possible biological function of CUX1 in glioma." (PMID 33542188, 2021). "In the present study, we first indicated that P75CUX1 is the most frequently expressed CUX1 protein isoform in glioma, with specifically designed antibodies for WB assays to distinguish all CUX1 isoforms." (PMID 33542188, 2021). "Analysis of public data sets revealed that CUX1 mRNA expression was overexpressed in glioma, including Low-grade glioma and GBM, as compared to NB." (PMID 33542188, 2021). "These signal pathways are also known to enhance mesenchymal features of glioma, and have been reported to be regulated by CUX1 in several cancers such as breast cancer." (PMID 33542188, 2021). "Mechanistically, this study found that P75CUX1 regulated epithelial–mesenchymal transition (EMT) process mediated via β-catenin, and CUX1/β-catenin/EMT is a novel signaling cascade mediating the infiltration of glioma." (PMID 33542188, 2021). "Herein, we first identified that P75CUX1 isoform exhibited consistent expression among three isoforms in glioma with specifically designed antibodies to identify all CUX1 isoforms." (PMID 33542188, 2021). "Furthermore, knockdown of CUX1 using siCUX1 or shCUX1 showed inhibition of migration, and invasion of glioma both in vitro and in vivo." (PMID 33542188, 2021). "Furthermore, we also observed a significant positive correlation between CUX1 and β-catenin mRNA expression levels by analyzing the mRNA data of glioma and NB tissues from TCGA and GTEx databases using GEPIA webserver." (PMID 33542188, 2021). "Furthermore, CUX1 knockdown suppressed migration and invasion of glioma cells both in vitro and in vivo." (PMID 33542188, 2021). "Moreover, in a cultured glioma cell line U-251, GSK3β was shown to interact with Akt and snail and CUX1 pathway and regulate ionizing radiation-induced epithelial-mesenchymal transition as well as migration and invasion." (PMID 34975828, 2021). "Besides, CUX1 was verified to promote the progression of glioma via multiple other signaling pathways, such as Hippo and PI3K/AKT." (PMID 33542188, 2021). "In summary, the present study demonstrated that P75CUX1 could serve as a poor prognostic indicator in glioma, and CUX1/ β-catenin/EMT axle plays a crucial role in glioma infiltration." (PMID 33542188, 2021). "However, isoforms expression status of CUX1 and its association with EMT in glioma remains uninvestigated." (PMID 33542188, 2021). "Besides, we also verified that CUX1 might regulate several other signaling pathways in glioma, such as Hippo and PI3K/AKT." (PMID 33542188, 2021). "CTSL is involved in ionizing radiation-induced epithelial mesenchymal transition and promotes glioma cell invasion and migration via the Akt/GSK-3 β/Snail and CUX1 pathways." (PMID 35855914, 2022).
glioma (continued). "The mechanism of correlation of CUX1 and EMT was the breakthrough finding because EMT is a well-recognized mechanism in glioma diffuse infiltration." (PMID 33542188, 2021). "However, the expression and role of the CUX1 isoforms in glioma remain unclear." (PMID 33542188, 2021). "Besides CUX1/ β-catenin/EMT axle, to complete the mechanism of P75CUX1 in glioma, our further investigation indicated that P75CUX1 also regulated the expression of several important targets in glioma, including Hippo and PI3K/AKT signaling pathways in glioma." (PMID 33542188, 2021). "Although the CUX1 mRNA expression in GBM was positively correlated with the prognosis as analyzed using TCGA_GBM data, no supportive evidence could establish the role of CUX1 mRNA as a prognostic indicator in GBM or glioma after combining CGGA and TCGA data." (PMID 33542188, 2021). "Whether a similar mechanism between CUX1 and WNT exists in glioma need more profound exploration." (PMID 33542188, 2021). "As CUX1 mRNA could not fully represent the expression levels of CUX1 isoforms in glioma, we performed the WB assays to distinguish the expression of CUX1 isoforms in glioma." (PMID 33542188, 2021).